IL2 (interleukin 2)
Diseases named in the same sentence as IL2 in open-access papers (continued):
Sharing a sentence is not in itself a finding about the gene and the disease.
tumor (continued). "In PDAC, the tumor microenvironment, indeed, stimulates an extensive production of pro-inflammatory cytokines, such as interleukin 2, 6, and 10, and growth factors, such as vascular endothelial growth factor, involved in tumor proliferation and local fibrotic reactions." (PMID 28353661, 2017). "Current research efforts include the development of cytokine variants with extended in vivo half-life and targeted action on precise lymphocyte subsets and tumor sites (i.e., engineered IL-2 “superkine,” IL-15Rα Sushi-Fc fusion protein; IL-15 tri and tetraspecific killer engagers)." (PMID 29181007, 2017). "However, the combination of IL-21 and IL-2 supports expansion while also increasing the ability of Vγ2Vδ2 T cells to kill tumor cells and produce inflammatory cytokines." (PMID 28239463, 2017). "Strikingly, efficacious tumour immunosurveillance due to tumour-specific CD4 + T cells was consistently related to increased local concentrations of both proinflammatory (IL-6, IL-1α, and IL-1β) and Th1-associated cytokines (IL-2, IL-12, and IFN-γ)." (PMID 29089667, 2017). "With regard to total cancer cell count, the results show that the IL-2 threshold to activate effector T-cell division is positively correlated with pretreatment tumour size, indicating the important role of anti-tumour effector T-cell proliferation in TME to limit tumour size without immunotherapy." (PMID 28931635, 2017). "The results obtained from IL-2 immunotherapy proved for the first time that the immune system could completely eradicate tumor cells under certain circumstances." (PMID 28927416, 2017). "An increase in mRNA levels of IL-2, IL-12p40, IL-12p70, and IL-15 correlated with their increased protein levels in splenocytes of bortezomib-treated tumor-bearing mice compared with untreated tumor-bearing mice." (PMID 28052005, 2017). "Indeed, establishing a higher dose plasma level and daily injections of recombinant human IL-2 for 16 days resulted in tumor regressions." (PMID 28955032, 2017). "Pre-treatment of the inactivated IL-2R+ tumor cells with IL2-GMCSF may provide the highest chance for inactivating tumor cells binding with the IL-2 part of IL2-GMCSF." (PMID 26850448, 2016). "Otherwise, chemotherapy can induce IL-2 and IFNγ secretion to trigger immunogenic cell death, and increase the permeability of tumor cells to granzyme B, thereby rendering them to be susceptible to CTL-mediated lysis even if they do not express the antigen recognized by CTLs." (PMID 26459255, 2016). "There are also phase 1 and 2 trials evaluating use of a recombinant fusion protein consisting of IL-2 with L19 human vascular targeting antibody (Darleukin, L19-IL2), which promotes lymphocyte and NK cell stimulation and immune-mediated tumor cell death, with less toxicity." (PMID 27660705, 2016). "Another group of non-tumor bearing mice was injected with PBMC+IL-2 as a control." (PMID 26802025, 2016). "The IL-2 stimulation of NK cells leads to a significant up-regulation of all NCRs and NKG2D receptors and to an increase in cytokine secretion, which is associated with enhanced cytotoxic activity against leukemic and tumor cells." (PMID 26982331, 2016). "Based on the opposing roles of different concentrations of IL-2 on normal lymphocytes and tumour cells that express the IL-2R, we propose that these differences could be used to develop strategies to treat tumours with these characteristics." (PMID 27293315, 2016). "This may be the reason why single T-cell therapy with CD8+ CTL was less effective in controlling tumor growth, as IL-2 is required to support survival of these cells." (PMID 27588200, 2016). "IL2 is a T cell proliferation factor and a cytokine with tumor growth inhibition properties." (PMID 26993326, 2016). "PBMC+IL-2 treated mice exhibiting NK cell expansion had complete tumor remission." (PMID 26802025, 2016).
tumor (continued). "Since we were not able to obtain tumor tissue from WAS patients, we next wanted to examine if we could correlate expression of WASp and IL-2 with tumor outcome in cancer patients." (PMID 27477778, 2016). "Moreover, our data demonstrated that tumor volume and tumor weight were significantly reduced in rTCS-treated or rTCS/IL-2-treated nude mice bearing PC3 xenograft tumor compared with control." (PMID 27015938, 2016). "However, the optimal exposure times of high-dose IL-2 to tumor-specific naïve CD8+ T cells remains to be determined." (PMID 27306834, 2016). "To test our hypothesis, we assessed the synergistic effects of Treg depletion and IL-2 neutralization using tumor growth sizes as outcomes." (PMID 26868634, 2016). "We demonstrate that this approach results in superior NK cell-mediated tumour immunotherapy with no adverse side effects associated with wild-type IL-2." (PMID 27650575, 2016). "Tumor cells and T cell lines were co-incubated overnight and assessed by IL-2 ELISPOT assay." (PMID 27192170, 2016). "Therefore, IL2-GMCSF greatly enhanced the anti-tumor effects of splenocytes compared to either IL-2/GM-CSF alone or their combination." (PMID 26850448, 2016). "Analysis of immune mediator expression in Pan02 tumours at day 29 revealed that αCD40 significantly upregulated the Th1 chemokine CXCL10 at the mRNA and protein level in Pan02 tumours, along with IL-2, perhaps explaining the expansion or increased infiltration of tumour CD8+ T cells." (PMID 26918344, 2016). "Moreover, if the BF-rTK survived in the tumor via IV administration, it would be assumed that BF-rTK stimulated the production of higher concentrations of cytokines (e.g., IL-1α, IL-1β, IL-2, IL-10, IL-17, GM-CSF, and MCP-1)." (PMID 27275821, 2016). "At present, based on our maintained high response rates in the post-selection era, tumour morphology represents the most sensitive and reliable predictor of IL2 response to date and may well have similar predictive effect in other newer immunotherapies." (PMID 27777776, 2016). "Furthermore, important cytokines involved in immune response activation are necessary for tumour elimination (i.e., IL-2 and IFN-γ)." (PMID 27293315, 2016). "The promotion of cell–cell interaction by IL2-GMCSF was stronger between DC2.4 cells and tumor cells than between splenocytes and tumor cells, suggesting that binding of IL2-GMCSF to DC2.4 cells may be critical to initiate specific immune response." (PMID 26850448, 2016). "When the cell-fusion cytokine complexes were injected to tumor region, the GM-CSF part of fusion cytokine may interact with DCs in vivo which is consistent with the stronger interaction between DCs and tumor cells mediated by IL2-GMCSF in vitro." (PMID 26850448, 2016). "However, IL-2 exposed CART cells had inferior anti-tumor efficacy in vivo compared to T cells expanded in the presence of alternative cytokines." (PMID 27409425, 2016). "CD4+ T helper cells exhibit a profound effect in initiating and maintaining anti-tumor immunity: secretion of Th1 cytokines such as IL-2 and IFN-γ promote CD8+ cytotoxic and natural killer cell function, as well as induction of MHC class II molecule expression on tumor cells." (PMID 27766079, 2016). "Additionally tumour cells are able to respond to IL-2, and these cells produce factors that enhance their growth and help them evade or regulate the immune response." (PMID 27293315, 2016). "IL-2 was a well-known cytokine with activity of suppressing tumor cell growth." (PMID 27015938, 2016). "IL-2 is a well-known molecule with activity of suppressing tumor cell growth." (PMID 27015938, 2016). "In addition, it is known that IL-2 favors the expansion of regulatory T cells that can inhibit the anti-tumor activity of the effector CART cells." (PMID 27409425, 2016).
tumor (continued). "ADT plus IL-2 neutralization (CX + AI) ranked two positions higher and vaccination plus Treg depletion (V + AR) one position lower in the type I outcome (instantaneous tumor size) than that in the type II outcome (average tumor size)." (PMID 26868634, 2016). "However, when tested in vivo, CART cells exposed to IL-2 ex vivo showed the least anti-tumor effect." (PMID 27409425, 2016). "As for IL-2, systemic IL-15-mediated toxicity might be circumvented by tailoring tumor-specific T cells to express IL-15." (PMID 27656185, 2016). "In addition, we found significantly more binding to 4T1 tumor cells by IgG containing culture supernatants of splenic B cells collected from the hosts subjected to B cell therapy plus IL-2 administration vs. B cell therapy only." (PMID 27528023, 2016). "In contrast to IL-2 alone, a stimulation of patient-derived NK cells with Hsp70 peptide plus IL-2 resulted in a reactivation of their cytolytic activity against Hsp70 membrane positive tumor cells." (PMID 27891129, 2016). "For instance, IL-2 has been extensively studied in tumor-targeting Salmonella expressing systems." (PMID 27190519, 2016). "Tumor growth and mean tumor doubling times (TDTs) in these groups (IL-2: 9.7 days, α-PD-1/α-CTLA-4: 6 days, α-PD-1: 8.7 days, α-CD137: 11.7 days, α-PD-1/α-CD137: 11 days) were statistically not significant from Control-treated mice that had a mean TDT of 9.2 days." (PMID 27160390, 2016). "Similarly, tumor antigen specific CD4+ Th1 cells attracted to the tumor microenvironment will secrete IL-2, TNF-α, and IFN-γ, creating an environment for enhanced activity of antigen presenting cells (APC)." (PMID 27766079, 2016). "PD-1 interaction with its ligand, PD-L1, aberrantly expressed on tumor cells, results in T cell inactivation and apoptosis and inhibited activation of tumor antigen-specific T cells by reducing the production of IL-2, IFN-γ, and stimulating IL-10 production." (PMID 27766079, 2016). "Together, IL2-GMCSF fusion cytokine promote diverse anti-tumor immune activities." (PMID 26850448, 2016). "Therefore, we used H22 oxter tumor-bearing mice model to evaluate expression levels of IL2 and its anti-tumor efficacy in vivo." (PMID 27736965, 2016). "As a corollary, IL-2 administration in mice may stimulate CD4+ T cell proliferation in tumor-bearing mice, and it is well-known that the Th2 cells can provide help for B cell function." (PMID 27528023, 2016). "Pretreatment with either MMF or DMF enhanced IL-2-activated NK cell killing of K562 tumor cells." (PMID 27807435, 2016). "IL-2 plays an important role in maintaining T cell activities, including anti-tumor activity." (PMID 27081854, 2016). "IL-2 mediates anti-tumor activity by activating tumor-specific T cells and NK cells." (PMID 27660710, 2016). "The in vivo results demonstrated in both immune competent C57BL/6 mice and nude mice that the tumor vaccine containing IL2-GMCSF and inactivated B16F10 cells (BF group) exerted the most remarkably protective effects in terms of both the tumor-free ratio and the final survival ratio." (PMID 26850448, 2016). "Therefore, IL2 has been demonstrated as a powerful foreign gene for elevating the anti-tumor effects of rNDVs." (PMID 27736965, 2016). "In the study described herein we investigate whether expression of T-bet and / or competition for IL-2 is important for Treg-mediated suppression of tumor immunity." (PMID 26433463, 2015). "However, in situ production of interleukin-2 (IL-2) and IL-15 is necessary to continually reactivate these infiltrating NK cells to prevent NK cell exhaustion and inhibition by the tumour milieu suppressor cellular and humoral factors." (PMID 26040463, 2015). "IL-2 either as a monotherapy or in combination with CTLA-4 blockade increased the proportion of less fully differentiated (CD27-CD11b-) NK cells as compared with the exhausted (CD11b+) NK cells within the tumor observed with CTLA-4 blockade alone." (PMID 25992289, 2015).
tumor (continued). "Although autologous NK cells persist in vivo for at least 1 week after infusion, they express lower levels of NKG2D, a key activating receptor, and may necessitate in vitro re-activation with IL-2 to lyse tumor targets." (PMID 26029215, 2015). "Furthermore, the tissue weights of the removed left kidney and bilateral lungs revealed that the combination of YM155 with IL-2 induced significant inhibition of tumor growth 14 days after treatment (respectively)." (PMID 26023798, 2015). "Thus, IL-2 production from TR-CD4 after direct tumor recognition was considered to be one of soluble factors that enhanced CD8+ T cell cytotoxicity." (PMID 26447332, 2015). "A major goal of the previously performed clinical phase I study was to test whether a treatment of tumor patients with autologous, ex vivo Hsp70 peptide plus IL-2 activated NK cells is safe and well tolerated." (PMID 25926832, 2015). "Interestingly, NK cells that had been stimulated with IL-2 only were significantly less efficient in the control of the tumor growth in mice." (PMID 25926832, 2015). "Tumor cells were treated with 10 nM of Gemcitabine for 24 hours and thereafter their sensitivities to NK cell cytotoxicity and degranulation activity were evaluated using IL–2 activated NK cells." (PMID 26439264, 2015). "In addition, both types of tumor cell lines triggered higher secretion of IFN-γ from IL-2+anti-CD16mAb treated NK cells when compared to IL-2 treated NK cells." (PMID 26247631, 2015). "Many studies confirm that IL-2 receptors are expressed in the surface of many tumor cells, a feature that when combined with IL-2 could inhibit tumor cell growth." (PMID 26508814, 2015). "Membrane-bound TGF-β on tumor-derived exosomes could also inhibit IL-2 induced T cell proliferation and promote Treg cell function." (PMID 26343191, 2015). "Intratumoral administration of IFN-α2, IFN-γ, TNF-α, and IL-2 significantly enhanced the anti-tumor effect of ovalbumin-specific CD8+ T-cell (OT-I) therapy, whereas GM-CSF increased tumor growth in association with an increase in immunosuppressive cell populations." (PMID 26107883, 2015). "Tumor lysis mediated by targeting T cells together with release of IL-2, IFN-γ, and GM-CSF may provide the milieu to induce immunization of endogenous immune cells to tumor associated antigens (TAA)." (PMID 25802762, 2015). "Since NK cells are considered a major player in mAb-mediated ADCC against tumor cells, reagents that can enhance NK cell activation, such as IL2, may be combined with mAb to improve the ADCC effect." (PMID 26284063, 2015). "The rationale was to costimulate tumor-reactive T cells with CD86 before IL-2 exposure." (PMID 26343191, 2015). "In the in vivo experiments, the mice in the PD-1 inhibited NK cells treatment group and IL-2-stimulated-NK cells treatment group displayed a slowest tumor growth (F = 308.5, P<0.01) and a slower tumor growth compared with control group (F = 118.9, P<0.01), respectively." (PMID 26266810, 2015). "Notably, a higher prevalence of TAA-specific T cells producing both IFN-γ and IL-2 was observed in these patients, thus suggesting a major clinical role of the multi-epitopic and polyfunctional anti-tumor T cell responses." (PMID 26116238, 2015). "Moreover, tumor cells stimulated by Ara-C induced CD4+ T cells to produce more IL2 (290.6 ± 33.5 pg/ml) than tumor cells alone (p < 0.01)." (PMID 26444983, 2015). "The combined treatment could markedly enhance cytotoxicity of CD8+ T cells and partially protect mice from tumor metastasis compared to IL-2 treatment alone." (PMID 26220086, 2015). "Consequently, inadequate IL-2 levels in the tumor microenvironment limits the extent of NK cell-mediated tumor rejection." (PMID 26648934, 2015).
tumor (continued). "Improving NK cell persistence in vivo via autocrine IL-2 and IL-15 stimulation, enhancing tumor targeting by silencing inhibitory NK cell receptors such as NKG2A, and redirecting tumor killing via chimeric antigen receptors, all represent approaches that hold promise in preclinical studies." (PMID 26113846, 2015). "To investigate if a combined therapy with another drug, able to selectively localize to the tumor structures, could enhance the antitumor effect of scFv OC-46F2, we chose L19-IL2, an immunocytokine composed of human scFv L19 and IL2." (PMID 26460958, 2015). "Thus it can be argued that local administration of IFN-α2, IFN-γ or IL-2 favorably alters the myeloid-lymphocyte balance and makes the tumor less resistant to immune cell attack." (PMID 26107883, 2015). "In conclusion, patients with low baseline IL-6 and anti-SEA/E-120 may respond well to Nap by triggering T cell activation and expansion (IL-2) paving the way for anti-tumour effects documented as prolonged OS." (PMID 25669986, 2015). "Pre-mNKs from mice receiving IM and IL-2 therapy could kill tumor ex vivo and reduce tumor burden in vivo via a TRAIL-dependent mechanism." (PMID 26405570, 2015). "Moreover, IFN-α2 and IL-2 increased the levels of activated tumor-infiltrating CD8+ T-cells concomitant with reduction in the CD8+ T-cell expression of anergy markers CTLA-4 and PD-1." (PMID 26107883, 2015). "Several studies have investigated IL-2 as a T cell growth factor that induce Fas-mediated elimination of Tregs and MDSCs from the tumor microenvironment and elicit synergistic antitumor responses coincident with the efficient removal of Tregs and MDSCs in cancer models." (PMID 26023798, 2015). "The early clinical trials based on adoptive cell transfer, utilized lymphokine-activated killer (LAK) cells generated from autologous PBMCs cultured in vitro with high doses IL-2 for 3–7 days in order to induce anti-tumor killer cells that mainly consisted of NK cells." (PMID 26594216, 2015). "In addition, MSCs themselves can produce therapeutic cytokines, such as IFN-β and interleukin-2 to provide for beneficial anti-tumor effects." (PMID 26255627, 2015). "In a dose-dependent manner, IL-2 is important for NK cell infiltration and killing of the tumor." (PMID 26648934, 2015). "A high serum level of IL-2 may saturate receptors and allow for a greater T-lymphocyte response against the tumor; therefore, high-dose regimens were created empirically as anticancer treatment." (PMID 26557408, 2015). "Since sAJ2 induce significant IL-10 secretion in untreated NK cells, and the levels substantially decrease when NK cells are activated with IL-2 or IL-2 + anti-CD16mAb, we aimed at determining whether such modulation also affects tumor differentiation." (PMID 26697005, 2015). "Combinational immunotherapy using antibodies to CTLA-4, PD-1/PD-L1, with small molecule inhibitors of indolamine deoxygenase (IDO), have also been shown to lead to improved tumor control and increased IL-2 production by tumor infiltrating lymphocytes (TILs) in an implantable melanoma setting." (PMID 25992292, 2015). "Notably, injections of IFN-α2, IFN-γ, TNF-α and IL-2 markedly improved the anti-tumor effect of ACT, while treatment with GM-CSF resulted in stimulation of tumor growth." (PMID 26107883, 2015). "Although the mechanism of this decrease is not understood, blocking the expansion of Tregs could improve tumor immunotherapy with IL-2 by taking advantage of the expansion of CD8+ effector T and NK cells." (PMID 25992289, 2015). "To assess whether the defect in B16F10 tumor control was due to NK cell dysfunction, we adoptively transferred IL-2 activated NK cells from TRPM2+/+ and TRPM2−/− mice into B16F10 tumor-bearing TRPM2−/− mice." (PMID 25879940, 2015). "A converse application of IL-2 targeted therapy is blockade of IL-2, which could theoretically be beneficial in the setting of cancer where depletion of Tregs could boost anti-tumor immunity." (PMID 25741338, 2015).